FLNA (filamin A)
Diseases named in the same sentence as FLNA in open-access papers (continued):
Sharing a sentence is not in itself a finding about the gene and the disease.
breast cancer (continued). "Cyclin D1/CDK4 complexes interact and phosphorylate the scaffold protein filamin A, a member of the actin-binding protein family, thereby controlling the invasion potential of breast cancer cells." (PMID 29066743, 2017). "Recent studies have shown that cyclin D1 interacts with and regulates FLNa expression in migrating breast cancer cells." (PMID 26009991, 2015). "The expression of the FLNa protein was detected in 63.54% of the breast cancer tissues, whereas the immunoreactivity of the FLNa antibody was extremely low in certain distant normal tissues." (PMID 24137390, 2013). "First, FLNa protein expression was assessed in the breast cancer and distant normal and benign breast tumor tissue specimens." (PMID 24137390, 2013). "The data showed that the FLNa protein was mainly detected in the cytoplasm of the breast cancer cells, mostly at the edge of the cells and in the basal cells or intercellular substance." (PMID 24137390, 2013). "The same authors also reported that local breast cancers during early development have a higher levels of filamin-A than late counterparts." (PMID 23388158, 2013). "The FLNa protein was overexpressed in breast cancer tissues compared with distant normal mammary gland and benign breast tissues." (PMID 24137390, 2013). "Semi-quantitative RT-PCR data showed the transcriptional regulation of FLNa overexpression in breast cancer." (PMID 24137390, 2013). "In breast cancer, it was reported that cyclin D1 interacted with the FLNa protein to affect the migration and invasion potential of breast cancer cells." (PMID 24137390, 2013). "The overexpression of FLNa in breast cancer was validated by RT-PCR, indicating transcriptional regulation of FLNa overexpression in breast cancer." (PMID 24137390, 2013). "One possible biomarker of breast cancer is filamin A (FLNa), which is a cytoskeletal protein with a molecular weight of 280 kDa that crosslinks actin filaments into orthogonal networks." (PMID 24137390, 2013). "In the present study, FLNa expression was demonstrated in the cytoplasm of the breast cancer cells, mainly at the edge of the cells and in the basal cells or intercellular substance." (PMID 24137390, 2013). "In the present study, the differential expression of FLNa mRNA and protein was analyzed in breast cancer tissue specimens in order to provide ex vivo data on the potential role of the FLNa protein in breast cancer." (PMID 24137390, 2013). "Although unable to interact with FlnA, the mutant AR still mediates androgen-induced DNA synthesis as shown by BrdU incorporation analysis of AR-negative human mammary cancer-derived MDA-MB231 cells ectopically expressing this mutant." (PMID 21359179, 2011). "The actin cross-linking protein filamin A suppresses focal adhesion disassembly and breast cancer cell invasion." (PMID 21931851, 2011). "This TNBC‐specific correlation appears to be linked to the relative level of filamin A. While HIF1α‐regulating factors are diverse, filamin A level is higher in TNBC compared to other subtypes of breast cancer, and filamin A cleavage is a critical factor in HIF1α activity in TNBC." (PMID 40151834, 2025). "Multiple studies have confirmed the expression of FLNa protein in breast cancer specimens." (PMID 38666944, 2024). "The available literature reports discussed in this review highlight the pivotal involvement of FLNa in processes related to the progression of breast cancer, including cell migration, invasiveness, angiogenesis, and gene expression regulation, as well as DNA repair and response to therapy." (PMID 38666944, 2024). "Studies confirming the overexpression of FLNa in breast cancer cells compared to normal breast tissue suggest that it may serve as a breast cancer marker." (PMID 38666944, 2024). "Filamin A is described as a potential driver of breast cancer metastasis." (PMID 40603632, 2024). "Putting all the data together, we speculate that FLNA could be one of the positive factors to breast cancer metastasis." (PMID 35359350, 2022).
breast cancer (continued). "Putting all the results together, we consolidated that FLNA could be a potential driver gene to metastasis of breast cancer, in particular triple-negative breast cancer." (PMID 35359350, 2022). "However, the expression of FLNA is decreased in breast cancer, which is negatively correlated with lymph node metastasis." (PMID 36105798, 2022). "In this study, we proposed that FLNA could be a positive factor in breast cancer metastases for the first time." (PMID 35359350, 2022). "For example, in breast cancer cells, the interaction of FLNA with cyclin D1 promotes migration and invasion, while on the other hand, the regulation of focal adhesion disassembly by FLNA leads to the suppression of breast cancer cell migration and invasion." (PMID 32545553, 2020). "Recently, FLNA has been considered to be a tumor-promoting protein with an important role in tumor development and metastasis, including bladder cancer, lung cancer, melanoma tumor and breast cancer." (PMID 31384171, 2019). "Filamin A was correlated to breast cancer development and progression in an ex vivo analysis." (PMID 29720730, 2018). "Indeed, a recent study showed that filamin A promotes migration and invasive potential of breast cancer cells through interaction with cyclin D1." (PMID 25944616, 2015). "However, we provide clinical evidence demonstrating that FLNa is frequently overexpressed in breast cancer specimens." (PMID 24137390, 2013). "It was observed that the FLNa protein was overexpressed in the breast cancer tissues compared with the distant normal mammary gland and benign breast tissues, and that this overexpression was associated with advanced stages, lymph node metastasis and vascular or neural invasion of breast cancer." (PMID 24137390, 2013). "Filamin A suppresses breast cancer cell invasion by inhibiting focal adhesion disassembly." (PMID 21931851, 2011). "This led to the conclusion that the absence of FLNa could serve as a prognostic marker to assess the risk of breast cancer metastasis and that targeting FLNa expression might offer a therapeutic strategy to reduce tumor metastasis in affected patients." (PMID 38666944, 2024). "Cyclin D1/Cdk4 specific phosphorylation of filamin A at S2152 and S1459 using mass spectrometry has been detected, suggesting that decreased filamin phosphorylation at S2152 and S1459 is associated with decreased wound healing-migration of MDA-MB-231 breast cancer cells." (PMID 38958472, 2024). "Furthermore, because of its involvement in processes important for cancer progression, FLNa could also become a target in breast cancer therapy." (PMID 38666944, 2024). "In summary, we speculate that FLNA likely promotes breast cancer metastasis in two different ways." (PMID 35359350, 2022). "The depletion of estrogen receptor α (ERα) affects the biomechanical properties of Breast cancer (BC) cells, which is related to the decrease of cytoskeletal proteins (F-actin, FLNA, and α-tubulin) and cytoskeletal regulatory proteins (Rho, Rac1, and Cdc42)." (PMID 34079763, 2021). "To date, there have been no studies reporting FLNa expression in ex vivo breast cancer tissue specimens; thus, the present study was proposed in order to detect FLNa expression in breast cancer tissue samples and to identify any associations between FLNa expression and clinicopathological data." (PMID 24137390, 2013). "Our data suggest that the results are robust in different NSCLC datasets and the key target genes identified (ITGA2B, FLNA, GRB2, FCGR2A, and APP, etc.)seem to also be strongly expressed in the breast cancer and pancreatic cancer datasets we analyzed." (PMID 41226816, 2025). "Model 1 was built using three proteins previously identified as potential biomarkers of breast cancer in blood and/or tissue: Cofilin 1 (CFL1, LGGSAVISLEGKPL), Alpha-2-HS-glycoprotein (AHSG, HTFMGVVSLGSPSGEVSHPR), and Filamin A (FLNA, SPFSVAVSPSLDLSK)." (PMID 33267867, 2020).
breast cancer (continued). "Model 2 included four candidate predictors specific for breast cancer in this study: Ras-related protein Rap-1A (RAP1A, LVVLGSGGVGK), Integrin alpha-IIb (ITGA2B, VYLFLQPR), FLNA (ANLPQSFQVDTSK), and Talin-1 (TLN1, LAQAAQSSVATITR)." (PMID 33267867, 2020). "The FLNa protein was expressed in 63.5% of breast cancer, with positive rates of 36, 66.7 and 84.6%, respectively, in stage I, II and III breast cancer patients (P<0.05)." (PMID 24137390, 2013). "The researchers concluded that FLNa knockout is not fatal in breast cancer cells, but it severely represses cell proliferation, invasion, and migration capabilities." (PMID 38666944, 2024). "Applying label-free proteomic quantitation method and statistical analysis, several differentially expressed proteins (DEPs) were identified in the serum of breast cancer patients compared to controls, including SBSN, ANG, PCOLCE, and WFDC3 (upregulated), and PFN1, FLNA, and DSG2 (downregulated)." (PMID 39990193, 2024). "Although FLNA was reported to be highly expressed in cancers, its connection with breast cancer metastasis has not been well investigated previously." (PMID 35359350, 2022). "After normalizing to the GAPDH mRNA levels, the expression level of the FLNa mRNA was 0.634±0.53 in the breast cancer tissues and 0.06±0.01 in the distant non-tumor breast tissues (P<0.05)." (PMID 24137390, 2013). "It was found that FLNA was overexpressed in breast cancer cells compared to normal breast tissue and the absence of FLNA could impede the formation of BRCA1 foci following DNA damage to promote breast cancer progression." (PMID 39126025, 2024). "As we continue to unravel the mysteries surrounding FLNa in the context of cancer, it is clear that this protein is one of the key elements for understanding not just how breast cancer develops, but also the pathways to effective treatment and metastasis prevention." (PMID 38666944, 2024). "Interestingly, the Pro-PrP isoform continues to possess the GPI anchor peptide signal sequence which is able to provide a binding motif for filamin A, which participates in modulating cancer cell proliferation and migration in colorectal cancer cells and the expression of BRCA1 in breast cancer." (PMID 33671884, 2021).
epilepsy (16 papers, 2013 to 2025). A brain disorder characterized by episodes of abnormally increased neuronal discharge resulting in transient episodes of sensory or motor neurological dysfunction, or psychic dysfunction. "Her medical history included intellectual disability, schizophrenia, epilepsy, hearing impairment, and hypothyroidism, which is consistent with the clinical manifestations of FLNA gene mutations." (PMID 40735484, 2025). "Mutations in the gene encoding the cytoskeletal protein FLNA are linked to disorders such as epilepsy and autism." (PMID 40365811, 2025). "Flna encodes filamin A, an actin cross-linking protein in which a loss-of-function mutation is associated with neuronal heterotopia and epilepsy." (PMID 34877936, 2021). "Identification of the underlying FLNA mutation should prompt inclusion in regular intensified medical care in an epilepsy center as well as cardiovascular surveillance by physicians familiar with the wide phenotypic spectrum of FLNA mutation carriers." (PMID 26471271, 2015). "Here, we report a novel variant of FLNA in a patient with epilepsy and PVNH." (PMID 39399465, 2024). "However, FlnA has been implicated in various other diseases that occur later in life such as epilepsy, Alzheimer’s disease, and certain malignancies." (PMID 29240780, 2017). "Tubulin genes play a key role in several pathways of cortical development such as other genes encoding microtubule-related proteins (i.e., Lissencephaly 1, Doublecortin, Filamin A or Reelin genes) and when mutated, may cause specific brain malformations strictly associated with epilepsy." (PMID 31269740, 2019). "This panel list of genes consists of preliminary evidence genes for epilepsy, Glycine Encephalopathy, FLNA, PTEN, and RANBP2 genes as well as Rett and ADs and related disorders." (PMID 39976384, 2025). "We focused on the role of FLNA in epilepsy, cell migration, cardiovascular development, and increased dendritic complexity." (PMID 41241686, 2025). "There are reports of filamin A pathology, as astrocytic inclusions, in human patients with epilepsy." (PMID 34322075, 2021). "More importantly, both FLNA knockdown and PTI-125 treatment reduced seizure activity in Rheb S16H mice, demonstrating a direct contribution of FLNA to epilepsy." (PMID 33897381, 2021). "While SZT2 and FLNA variants were common in epilepsy, there were no reports regarding photosensitivity." (PMID 36034301, 2022). "As no other pathogenic variants were found in epilepsy-related genes, this FLNA variant likely caused West syndrome but with no PVNH." (PMID 33298907, 2020).
Melnick-Needles syndrome (13 papers, 2014 to 2025). A otopalatodigital syndrome spectrum disorder and is associated with a short stature, facial dysmorphism, osseous abnormalities involving the majority of the axial and appendicular skeleton resulting in impaired speech and masticatory problems. "Mutations in FLNA cause a large spectrum of congenital malformations during embryonic development, including Melnick–Needles syndrome (MNS)." (PMID 36734119, 2023). "Melnick-Needles syndrome (MNS) is an extremely rare osteochondrodysplasia caused by a mutation of FLNA, the gene encoding filamin A. MNS is inherited in an X-linked dominant manner." (PMID 32814550, 2020). "FLNA gene encodes an actin-binding protein and mutations of the FLNA gene have been found in OPD II, Melnick-Needles syndrome, or frontometaphyseal dysplasia." (PMID 26451378, 2015). "Skewed X-inactivation is observed in females heterozygous for FLNA Melnick-Needles syndrome and OPD mutations, suggesting that cells need normal FLNA to survive." (PMID 25614868, 2014).
colorectal cancer (12 papers, 2013 to 2025). A primary or metastatic malignant neoplasm that affects the colon or rectum. "Taken together, these results suggested that DKC1, CSE1L and NSUN5 were dramatically overexpressed while FLNA was significantly downregulated in colorectal cancer." (PMID 36319976, 2022). "AZGP1 is a useful diagnostic biomarker found in the tissues and serum of Chinese CRC patients and it promotes epithelial-mesenchymal transition (EMT) in colorectal cancer via the filamin A-mediated focal adhesion pathway." (PMID 34698109, 2021). "They found that ~50 % of the colorectal cancer had moderate to high levels of filamin-A, whereas filamin-A was undetectable in normal colon glandular cells." (PMID 23388158, 2013). "Given that TALIN-1, MRE11, and CCT8 interact with E-cadherin, that FASN, FLNA, and DDX3X are implicated in EMT, and that FKBP4 expression is upregulated in colon cancers, we examined E-cadherin expression in human colorectal carcinoma HCT116 cells under the FKBP4 knockdown." (PMID 41203126, 2025). "Taken together, our proteomic screen suggests a common mechanism of AGR2 acting over FLNA and NPM3 proteins in SW480 and SW620 colorectal cancer cell models, as demonstrated by both the overexpression and silencing of AGR2." (PMID 39300184, 2024). "For FLNA, a study reported that FLNA could directly regulate the metastasis and EMT of chemoresistance colorectal cancer cells." (PMID 37179366, 2023).
lung carcinoma (12 papers, 2013 to 2023). "In fact, an overexpressed FLNA was found in multiple types of cancer, including prostate, breast, lung cancer, squamous cell carcinoma, hepatic cholangiocarcinoma, parathyroid carcinomas, cervical cancer and pulmonary neuroendocrine tumours." (PMID 38068896, 2023). "Silencing of FLNa expression in lung cancer cell lines can promote proliferation, migration and invasiveness." (PMID 36527824, 2023). "One of the genes found to be downregulated, FLNA, was reported to decrease drug resistance of lung cancer cells to gefitinib." (PMID 35342659, 2022). "After stratifying the lung cancer patients based on their status of cigarette smoking, e.g., never-smoked or smoked, it was found that higher expression level of filamin A predicts poorer overall survival of the patients who were never-smoked." (PMID 25944616, 2015). "Clinically, we found that increased expression of filamin A predicts poorer overall survival of the lung cancer patients with adenocarcinoma." (PMID 25944616, 2015). "Previous studies have shown that FLNa expression is positively associated with VEGF, an angiogenesis regulator, in lung cancer." (PMID 24137390, 2013). "Down-regulation of filamin A in breast and lung cancer cell models has been shown to stimulate proliferation, migration, invasion and metastasis formation, and alternative splicing of filamin A has been reported to have a role in differentiation and organogenesis." (PMID 30241319, 2018). "FLNa is a widely expressed molecular scaffold protein that organizes filamentous actin into networks and stress fibers, is involved in cell motility and invasion, and is frequently overexpressed in cancers, including lung cancer." (PMID 26009991, 2015). "In initial analysis, we found that the expression level of filamin A did not distinguish poorer or better survival times of the patients when all types of lung cancers were included." (PMID 25944616, 2015).
frontometaphyseal dysplasia (10 papers, 2009 to 2025). Frontometaphyseal dysplasia (FMD) belongs to the otopalatodigital syndrome spectrum disorder and is characterized by anomalous ossification and skeletal patterning of the axial and appendicular skeleton, facial dysmorphism and conductive and sensorineural hearing loss. "FLNa mutations are also associated with a group of X-linked skeletal anomalies including frontometaphyseal dysplasia (FMD) and cardiovascular defects such as familial cardiac valvular dystrophy, the most common indication for valvular surgery." (PMID 19293932, 2009). "Besides, these researchers found that FLNA mutations were also responsible for oto−palato−digital syndrome, types 1 (OPS 1) and 2 (OPS 2), and frontometaphyseal dysplasia with overlapping clinical phenotypes." (PMID 21274303, 2009). "Furthermore, clustered missense mutations in FLNA have been identified in a diverse spectrum of congenital malformations in humans, including otopalatodigital syndrome (OPD), frontometaphyseal dysplasia (FMD) and Melnick–Needles syndrome (MNS)." (PMID 23388158, 2013).